IL6 (interleukin 6)
Diseases named in the same sentence as IL6 in open-access papers (continued):
Sharing a sentence is not in itself a finding about the gene and the disease.
COVID-19 (continued). "Taken together, while the age and concomitant comorbidities of COVID-19 patients largely determine the clinical course of COVID-19, D-dimer, CRP, ferritin, cardiac troponin I and IL-6 may act as predictors for severe COVID-19." (PMID 34262116, 2021). "The analysis of the plasmatic levels of inflammatory chemokines and cytokines in patients with COVID-19 and MIS-C showed higher levels of IL-6, CXCL8, CCL2/MCP-1, CXCL9/MIG, and CXCL10/IP-10 in MIS-C, whereas CCL5 levels were significantly higher in the COVID-19 group." (PMID 33841438, 2021). "Due to observations of low vitamin D levels and high IL-6 expression in SARS, MERS, and COVID-19 patients, vitamin D supplementation may be considered as a useful measure to prevent dangerous symptoms from developing in viral respiratory infections." (PMID 34452063, 2021). "Moreover, high levels of IL-1β and IL-6 have been identified in SARS-CoV-2-infected subjects, and single-cell transcriptomic analysis of peripheral blood in COVID-19 patients also show increased subsets of IL-1β-producing monocytes." (PMID 33790857, 2021). "At present, one RCT is aiming to evaluate the efficacy of PJ on inflammatory parameters, C-reactive protein (CRP), interleukin 6 (IL-6), erythrocyte sedimentation rate (ESR), and complete blood count (CBC) in mild to moderate COVID-19 patients (IRCT20150711023153N2)." (PMID 34796029, 2021). "IL-6 and CRP were the strongest predictors of severity in hospitalized patients with COVID-19." (PMID 33305624, 2021). "During the second phase of COVID-19, pneumonia patients exhibit features of macrophage activation syndrome (MAS) in which macrophages play a major pro-inflammatory role by releasing pro-inflammatory cytokines such as IL-6, IL-8 and CCL23." (PMID 33446817, 2021). "Our synthesized results revealed significantly lower levels of immune cells in CD3+ T, CD4+ T, CD8+ T, B and NK cells, higher levels of cytokines (TNF-α, IL-5, IL-6 and IL-10) and higher levels of chemokines (MCP-1, IP-10 and eotaxin) in severe cases compared with mild cases of COVID-19." (PMID 34344353, 2021). "This inflammatory transcriptional signature, as shown by RNA Seq and confirmed by qPCR for Il-6, type I IFN (Ifn-β) and Cxcl10 is consistent with the recent neuropathological description of deceased patients with COVID-19, where microgliosis was seen in the olfactory bulb." (PMID 33941622, 2021). "Like COVID-19, increased production of multiple pro-inflammatory chemokines and cytokines is a prominent feature of mycobacterial IRIS, including increased production of TNF-α and IL-6." (PMID 33841434, 2021). "In adults, according to the study of 99 COVID-19 patients with mean age of 55 and mostly men 68%, the disease in laboratory tests manifests by an increase in the total number of C-reactive protein (CRP), Interluekin-6 (IL-6), neutrophils, and leucocytes." (PMID 34063964, 2021). "The most frequently used blood tests useful in COVID-19 patients with cardiovascular involvement are: N-terminal (NT)-pro Brain Natriuretic Peptide (BNP)/BNP, troponin, D-dimer, procalcitonin, full blood count, IL-6 and ferritin." (PMID 33916917, 2021). "Therefore, COVID-19 patients with CHD were four times more likely to die than average COVID-19 patients, with an elevated level of proinflammatory cytokines such as IL-6, CRP, and procoagulant factors such as D-Dimer20." (PMID 34903765, 2021). "The present study aimed to investigate whether serum levels of NLRP3, HMGB1, IL-6, IL-10, angiotensin II and ACE2 were different in COVID-19 patients with headache." (PMID 34384355, 2021). "The identified crucial cytokine panel, including IL6, IL1β, IL10, CXCL10, IGF1, and GALECTIN-1, may offer the selective targets to improve the efficacy of COVID-19 therapy." (PMID 34238338, 2021). "Moreover, compared to healthy subjects, cirrhotic and COVID-19 patients had higher levels of CRP and IL-6." (PMID 34945736, 2021).
COVID-19 (continued). "Immunotherapeutic protocols for COVID-19 include polyclonal antibody by plasma therapy, polypeptide hormone for the maturation of T cells, immunoglobulins, ACE2 immunoadhesin and a monoclonal antibody against the interleukin-6." (PMID 33494244, 2021). "A recently published meta-analysis showed that IL-6 levels in patients with severe COVID-19 were higher than those in non-severe COVID-19 patients (MD: 38.6 ng/L, 95% CI: 24.3–52.9 ng/L), the trend of difference was consistent with our study." (PMID 33557779, 2021). "Some type 2 cytokines (IL-4, IL-9, IL-13, etc.)have inhibitory effects on the production of proinflammatory cytokines (IL-1β, IL-6, TNF-α, etc.), the overactivation of which have been proposed as a potential key mechanism of protection against COVID-19 to some extent." (PMID 35082829, 2021). "The results suggested that Tocilizumab therapy did not affect the percentage of Mo-MDSC, PMN-MDSC, nor the sera IL-6 levels in severe COVID-19 patient group." (PMID 33692788, 2021). "According to the results, TT, ferritin and LDH are the best parameters to distinguish mild to moderate COVID-19 patients (non-ARDS group) from severe patients (ARDS group) followed by IL-6 and D-dimer." (PMID 34439469, 2021). "Indeed, we found a close and positive correlation between IL-6 levels in plasma and its levels in BALF from patients with critically ill COVID-19." (PMID 34379684, 2021). "The ESR and levels of CPR, IL-6, LDH, high-sensitivity cardiac troponin I, N-terminal prob-type natriuretic peptide, creatine kinase, D-dimer, ferritin, creatinine, liver enzymes, and procalcitonin are commonly high in severe COVID-19 cases." (PMID 34295915, 2021). "However, there were significantly higher levels of IL-6 and CRP in patients with immune dysregulation and MAS compared to patients with intermediate COVID-19." (PMID 34452063, 2021). "More interestingly, also a broad spectrum of cytokines/chemokines inhibitors not specifically targeting IL-6 and its secretion pathways was applied to counteract COVID-19." (PMID 33981314, 2021). "Zn supplementation may be able to reduce inflammatory cytokines (IL-6 and IL-1β), enhancing the protective type-I IFN response in COVID-19." (PMID 33921297, 2021). "Indeed, the plasma levels of interleukin-2 (IL2), interleukin-6 (IL-6), tumor necrosis factor α (TNFα), and C-reactive protein (CRP) are markedly elevated in COVID-19 patients." (PMID 34326911, 2021). "In addition, COVID-19 group showed increased TNF-α level and decreased IL-2, IL-6, IL-10, and IFN-γ levels." (PMID 34667157, 2021). "In particular, 25OHD and IL-6 levels are respectively lower and higher in severely symptomatic COVID-19 patients admitted to ICU, as compared to not critically ill patients, and in non-survivors as compared to survivors." (PMID 37386621, 2021). "As there is an inverse relationship between TNF-α expression and T cell recruitment, similar to IL-1RA and IL-6, elevated TNF-α expression may further contribute to inflammatory progression of COVID-19 patients to develop ARDS or AKI." (PMID 34131192, 2021). "Severe COVID-19 patients exhibit high level of pro-inflammatory macrophages, neutrophils and monocytes, which contribute to the cytokine storm with very high plasma levels of TNF, IL-12, IL-6, IL-10, IL-7, G-CSF, IP-10, MIP1α, and MCP1." (PMID 33664772, 2021). "In the COVID-19 cytokine storm, IL6 is one of the most highly expressed cytokines: one of the main indicators of poor prognosis in SARS-CoV-2 infection is represented by elevated serum levels of IL6." (PMID 34638236, 2021). "PBM stabilize the function of the immune system (drop the level of pro-inflammatory cytokines such as IL-1β, IL-6, IL-8, TNFα, and MCP-1 and improve the balance of IL-10) in severe COVID-19 cases, decreasing the impact of cytokine storm as the main cause of high mortality in ARDS patients." (PMID 34066560, 2021).
COVID-19 (continued). "Taken all the data together, we found significant elevations of circulating HMGB1, NLRP3 and IL6 levels in COVID-19 patients with headache compared to COVID-19 patients without headache." (PMID 34384355, 2021). "IL-6, MCP-1, TNFα and other immune markers, particularly those involved in myeloid cell recruitment and function, have been identified as markers that are important in the development of COVID-19." (PMID 34452519, 2021). "It was also found that the inflammatory factors IL-2R, IL-6, and C-reactive protein (CRP) were elevated in COVID-19 patients, and IL-2R and IL-6 had certain advantages in predicting the severity of the disease compared with traditional indicators (lymphocyte count and CRP)." (PMID 34164371, 2021). "A systemic inflammatory storm in COVID-19 may also contribute to the amplification of the GBS’s dysimmune process, related to increased blood inflammatory markers (e.g., CRP, IL-6, TNF-α, and IL-1)." (PMID 34078305, 2021). "COVID-19 patients display high levels of both inflammatory cytokines and chemokines (IL-1a/β, IP-10, MCP-1), with severe cases showing elevation in TNFα, IL-1, IL-6, IL-18, IL-8, IL-10, MCP-1 and MIP-1A." (PMID 33803997, 2021). "Our findings indicated that patients with severe COVID-19 who progress to ICU admission and/or death are characterized by a markedly disturbed IR, mainly involving elevated serum levels of IL6, IL15, sIL1RII, sRAGE, IP10 and MCP3 in the first week of hospitalization." (PMID 34829906, 2021). "To date, several clinical and biochemical parameters have been used to predict the severity of COVID-19, including the following: C-reactive protein (CRP), serum amyloid A (SAA), interleukin (IL)-6, lactate dehydrogenase (LDH), white blood cell count, d-dimer, cardiac troponin and platelet count." (PMID 34667241, 2021). "Furthermore, mean concentrations of all five cytokines in the influenza (CS) group and IL-6, IL-8, TNF-α in the burn group were significantly greater than in COVID-19 patients (p < 0.01)." (PMID 33921604, 2021). "Similarly, the pooled mean IL-6 level was much higher in patients with hyperinflammatory ARDS (1558.2 pg/ mL) and patients with sepsis (983.6 pg/mL) compared with COVID-19 patients." (PMID 34199506, 2021). "Finally, we evaluated changes in angiotensin II, IL-6, and CRP levels in four patients who were administered ARBs to determine the change of angiotensin II due to ARBs in COVID-19 patients." (PMID 34285712, 2021). "Patients with obesity have higher concentrations of circulating tumor necrosis factor-alpha (TNF-a), interleukin-6, and C-reactive protein (CRP); this low grade chronic inflammatory state may be involved in initiating cytokine storms in patients with COVID-19." (PMID 34068824, 2021). "The network constructed for comparing patients with sepsis to patients with COVID-19 ARDS also suggested an upregulation of several key molecules relevant for the pathogenesis of COVID-19 ARDS which included TLR4, IL6, and - in particular - STAT1 (signal transducer and activator of transcription 1)." (PMID 34956213, 2021). "This suggests that antibodies that target IL-6 and TNF-signaling may restore NK cell functions in COVID-19 patients." (PMID 34578460, 2021). "Several lab tests such as IL-6, CRP and white blood cell subset counts may help predict the severity of COVID-19 during the patient’s hospital course if obtained when the patient first presents to the hospital." (PMID 34567235, 2021). "In particular, a meta-analysis has demonstrated a nearly 3-fold higher serum levels of IL-6 in patients with complicated COVID-19 when compared with those patients with non-complicated disease." (PMID 33777042, 2021). "Moreover, plasma from severe COVID-19-ARDS patients exhibit high IL-6 and PAI-1 levels and the IL-6 trans-signalling/PAI-1 axis has been related to endothelial dysfunction." (PMID 33596401, 2021).
COVID-19 (continued). "Comparative proteomics identified statistically robust overexpression of several inflammatory cytokines, specifically IL6, IL18, CCL7, CXCL10, and CXCL11, which could be targeted to prevent untoward immune-inflammatory effects in COVID-19 patients." (PMID 35145507, 2021). "Based on these data, our results suggest that the levels of the inflammatory biomarkers such as IL-6, CRP, and D-dimer might be related to the aggravation and deterioration of COVID-19, while lymphocytes might be used as a predictor of immune protection." (PMID 34712742, 2021). "A reduction in serum levels of IL-6, IL-1β, and TNF-α, rapid recovery of circulating T and B cell frequencies, and increased antibody production against the SARS-CoV-2 spike protein has been reported in severe COVID-19 cases treated with this agent." (PMID 34590796, 2021). "Compared with survivors, the level of IL-6 increased significantly in non-survivors, and it was considered as a predictor of mortality in COVID-19 patients." (PMID 34088317, 2021). "The severity of COVID-19 is attributed to the inflammatory status, presented as an increased inflammatory biomarker such as C-Reactive Protein (CRP), Interleukin 2 (IL-2), and Interleukin 6 (IL-6), which are predictors of mortality." (PMID 34903765, 2021). "The hyper inflammation and cytokine storm, common in COVID-19 patients, with an elevation in IFN-γ, IL-1β, IL-6, IL-17, and TNF, promotes muscular proteolysis, decreased protein synthesis, and satellite cells dysfunction, possibly another mechanism of muscle wasting in these individuals." (PMID 33613573, 2021). "The level of IL-6 in non-survivors is higher than that in survivors of COVID-19, indicating that increased levels of IL-6 in peripheral blood are closely related to worsening of the disease and poor prognosis." (PMID 34603047, 2021). "The association of higher CRP with worse outcomes may be due to the severity of the disease consistent with the ‘cytokine storm’ theory of COVID-19, where the innate immune system is activated releasing TNF-alpha, IL-6 and IL-1." (PMID 33683344, 2021). "At the level of cytokines/chemokines, patients with critical COVID-19, compared to mild-moderate COVID-19 patients, showed a tendency to gain a highly correlated (and expanded) cluster of IL-1 cytokines as well as a tendency of an IFN-γ/IL-6 cluster to gain correlation with TNF-α." (PMID 34226537, 2021). "The cytokine IL-6, in particular, appears to be associated with a more severe disease course, as higher levels of IL-6 were observed in non-survivors compared to survivors of COVID-19." (PMID 33824998, 2021). "It was reported that IL-6 levels were around three-times higher in the severe COVID-19 patients than the non-severe patients." (PMID 34538093, 2021). "Studies have shown that compared with that of mild cases, plasma levels of IL2, IL6, IL7, IL10, G-SCF, IP10, MCP1, ferritin, and TNFα in severe cases of COVID-19 were elevated, indicating that the participation of these cytokines contributes to the pathogenesis of deterioration." (PMID 34305916, 2021). "Based on these evidences, CRP, IL6 and procalcitonin levels may serve as potential markers for predicting progression of MHD patients with COVID-19." (PMID 33967613, 2021). "IL-6 and D-dimer were also shown to be greater in COVID-19 non-survivors vs. survivors, and higher levels of the acute phase proteins CRP and SAA in plasma have been associated with more severe disease and poorer outcomes in patients with COVID-19." (PMID 33800954, 2021). "Another study showed that Shufeng Jiedu prescription may prevent COVID-19 through its active ingredients likely quercetin, luteolin, wogonin, and kaempferol by targeting TNF, IL-10, IL-2, IL-6, STAT1, and CCL-2." (PMID 34861881, 2021).
COVID-19 (continued). "Biomarkers indicating rapid deterioration in COVID-19 patients are mostly represented by troponin I (TnI), CRP, erythrocyte sedimentation rate (ESR), D-dimer, progressive deterioration of lymphocyte counts and elevated inflammatory markers (IL-6, TNF-α)." (PMID 33916917, 2021). "Out of 76 patients, 48 patients of COVID-19 positive and 28 patients of COVID-19 negative polymerase chain reaction (PCR) were assessed for thyroid functions, IL-6, and Procalcitonin between moderate, severe, and critical pneumonia on HRCT." (PMID 33784355, 2021). "The CpG sites are common targets of viral genome and can be recognized by Toll-like receptors (TLRs) that results in release of pro-inflammatory cytokines including type- I interferon, IL-6, IL-12 and TNF-α those play key role in severe COVID-19 including lung tissue damage." (PMID 34458642, 2021). "Our aim was to determine if cardiac adipose tissue, combined to interleukin-6 levels, could predict adverse short-term outcomes, death and ICU requirement, in COVID-19 diabetic patients during the 21 days after admission." (PMID 34384426, 2021). "Pro-inflammatory cytokines and chemokines are increased in COVID-19, one of the reasons being the activation of the NF-κB and STAT3 pathways, leading to the activation of IL-6, which results in the release of pro-inflammatory cytokines and chemokines, activated T-cells, and activated B-cells." (PMID 33912588, 2021). "Considering the role of IL-6 pathway in the pathogenesis of severe COVID-19 and the confirmed LVL ability to block the IL-6 signaling, as well as its safety and good tolerability, we conducted a phase III clinical study to evaluate the efficacy and safety of LVL in subjects with severe COVID-19." (PMID 34586459, 2021). "Treatment with TNF-, IL-17-, and IL-6-inhibitors was not reported to be changed by the treating rheumatologists because of COVID-19 vaccination." (PMID 34498112, 2021). "In particular, IL-8, IL-6, and TNF-α levels were found to be significantly elevated in the sera of patients with COVID-19 compared with those of healthy donors or with plasma isolated from chimeric antigen receptor-modified T cell-treated patients with no cytokine release syndrome." (PMID 33572938, 2021). "First reports suggest that administration of MSCs is safe in patients with ARDS and may limit the cytokine storm (by reducing the levels of C-Reactive Protein, IL-6 or TNF-α) and improve oxygenation in severe COVID-19 patients." (PMID 34887773, 2021). "The combination of IL-6 and SARS-CoV-2 RNA may reflect more directly the critical pathogenesis of COVID-19 deterioration, composed of viral overload and hyperinflammation in affected lung, compared to the combination of clinical and laboratory data." (PMID 34379684, 2021). "Clinically, targeting IL-1β, IL-6, and TNF-α have gained some success in severe COVID-19 patients." (PMID 34150848, 2021). "Age, sex, BMI, race, COVID-19 disease severity, Charleston Comorbidity Index, COPD, C-reactive protein (>150 mg/L), interleukin-6 (>80 mg/L), ferritin (>2,000 ng/L), D-dimer (>2.0 mg/L), use of anticoagulation, use of corticosteroids, and smoking (current and former)." (PMID 34222281, 2021). "There was a clear dose-effect relationship between increasing values of IL-6 and the proportion of patients with severe COVID-19 in both MAFLD and non-MAFLD patients." (PMID 33763027, 2021). "Consistent with systemic inflammation, COVID-19-derived PBMCs but not HC cells spontaneously released IL-1β, and also IL-6 and TNF-α ex vivo (respectively)." (PMID 35095880, 2021). "The authors propose that serum IL-6 and tumor necrosis factor-alpha (TNF-α) levels should be considered in the management and treatment of patients with COVID-19 to stratify prospective clinical trials, guide resource allocation, and inform therapeutic options." (PMID 33747583, 2021).